GDF15 (growth differentiation factor 15)
Diseases named in the same sentence as GDF15 in open-access papers (continued):
Sharing a sentence is not in itself a finding about the gene and the disease.
Hyperglycemia (22 papers, 2013 to 2025). An increased concentration of glucose in the blood. "Recent pre-clinical and clinical studies of T2DM suggest that GDF-15 expression is also increased by oral metformin treatment and that the beneficial effects of metformin on weight loss (and associated hyperglycaemia) may be mediated by metformin-induced GDF-15 acting centrally to suppress appetite." (PMID 34663793, 2021). "The collagen network produced by fibroblasts was similarly compromised by hyperglycemia or GDF15 downregulation." (PMID 40174478, 2025). "We discovered that the NR2F2–MTERF3–GDF15 axis is involved in hyperglycemia-induced repression of oxidative metabolism in the skin, suggesting potential roles for MTERF3 and GDF15 in glucose homeostasis and dermal resilience." (PMID 40174478, 2025). "Exposure to glucose at 6.5 mM (upper normoglycemia boundary) and 12 mM (validated hyperglycemia) modulated GDF15 and MTERF3 expression, highlighting a highly sensitive mitochondrial repression mechanism." (PMID 40174478, 2025). "In contrast, GDF15 supplementation fully rescued hyperglycemia-induced bioenergetic and metabolomic alterations, suggesting a pharmacological strategy to mitigate hyperglycemic damage in the skin." (PMID 40174478, 2025). "In this study, higher GDF-15 levels were related to lower fetal growth percentiles in the third trimester, suggesting a putative protective function of GDF-15 against hyperglycemia-induced excessive fetal growth in GDM." (PMID 40283592, 2025). "In mice, GDF15 also appears to recruit the glucose-releasing and hyperglycemia-promoting hormone corticosterone, further mobilizing energetic resources to fuel energy-starved ISR-positive and GDF15-secreting cells and tissues." (PMID 38566850, 2024). "When substituting MS with its components, only hyperglycemia was positively correlated with GDF-15 levels." (PMID 37152921, 2023). "The exact role of GDF-15 in the hyperglycemia seen in prediabetes needs to be clarified with further studies." (PMID 27642607, 2016). "In an in vitro study, hyperglycemia induced GDF-15 expression, which resulted in umbilical endothelial cell apoptosis." (PMID 27056183, 2016). "In patients with CAD undergoing PCI with stent implantation, GDF-15 is determined by advanced age, acute and chronic hyperglycemia, inflammation and CKD." (PMID 27056183, 2016). "Understanding the interplay of NR2F2, MTERF3, and GDF15 broadens our grasp of hyperglycemia's tissue-specific impacts and may inform future therapeutic strategies targeting mitochondrial health." (PMID 40174478, 2025). "While GDF15 may rescue aspects of metabolic dysfunction, chronic hyperglycemia in vivo involves additional inflammatory pathways that may override this protective response." (PMID 40174478, 2025). "Thus, our data reveal a concerted repression of mitochondrial function in the human dermis driven by the interplay among NR2F2, MTERF3, and GDF15, offering a new perspective on hyperglycemia-induced tissue alterations." (PMID 40174478, 2025). "•NR2F2 activates MTERF3 and inhibits GDF15 upon hyperglycemia." (PMID 40174478, 2025). "In conclusion, in this pilot study, an inverse association between circulating GDF-15 levels and fetal growth in late pregnancy was observed in patients with GDM, suggesting a possible protective effect of GDF-15 against hyperglycemia-related excessive fetal growth." (PMID 40283592, 2025). "Increased circulating GDF15 could reduce appetite, thus delaying hyperglycemia and β cell exhaustion in db/db mice." (PMID 34113829, 2021).
Hyperglycemia (continued). "Notably, different GDF15 doses were used here: a higher, supraphysiological concentration (100 nM or 3000 ng/mL) effectively rescued hyperglycemia-induced metabolomic changes, while low nanomolar doses relevant to normal or mildly elevated plasma levels enhanced OXPHOS function." (PMID 40174478, 2025). "Additionally, confounding factors affecting circulating GDF15, such as food intake, hyperglycaemia, informal use of metformin, and strength of stress in each individual, could not be controlled in this study." (PMID 40142684, 2025). "Fibroblast haptotaxis declined under hyperglycemia or when GDF15 or TFAM were silenced, and skin reconstruction was blocked by GDF15 knockdown." (PMID 40174478, 2025). "Additionally, research should look to explore the potentially additive effects of hyperglycaemia, and other factors involved in the T2DM milieu, on the expression and circulating concentrations of GDF-15." (PMID 34663793, 2021). "Interestingly, administration of a high glucose load resulted in a rise in serum GDF-15 concentrations in both non-obese and obese individuals suggesting a potential direct role of hyperglycaemia on increased circulating GDF-15 concentrations." (PMID 34663793, 2021). "However, GDF15 expression did not appear to correlate with nutrient-related abnormalities, such as hyperglycemia (defined by HbA1c and RBG), hyperlipidemia (defined by TG and TC) or age." (PMID 32671100, 2020).
renal failure (22 papers, 2016 to 2025). "Moreover, in DN patients, high levels of GDF15 are associated with a decline in estimated glomerular filtration rate and faster progression to kidney failure." (PMID 32977372, 2020). "Compared to studies including healthy controls or patients with chronic atherosclerotic cardiovascular disease, patients with stable kidney failure on maintenance HD displayed markedly higher levels of circulating GDF-15." (PMID 37008733, 2023). "Compared to the study, all patients in this study had severe kidney failure and much higher GDF-15 concentrations than the previous study." (PMID 34441955, 2021). "Thus GDF15, sTfR, hepcidin 25 and zonulin may all be involved in iron metabolism, so may form new biomarkers of ferric management and one or more may ultimately serve as a predictor for MM-associated kidney failure." (PMID 31683939, 2019). "However, we could not demonstrate that dialysis rates were increased, which is thought-provoking because GDF-15 is a biomarker for the prediction of kidney failure." (PMID 34221186, 2021). "Likewise, with NT-proBNP values that may be adulterated by renal insufficiency or significant valvular disease, GDF-15 has to be evaluated simultaneously with other inflammatory parameters in order to rule out significant infections or even septic conditions." (PMID 31252588, 2019). "The global genetic deletion of Gdf15 did not result in any spontaneous renal insufficiency or significant proteinuria." (PMID 38607075, 2024).
cardiomyopathy (21 papers, 2015 to 2025). A disease of the heart muscle or myocardium proper. "Hamp−/−/shFxn mice exhibited significantly shorter lifespans, aggravated cardiomyopathy as assessed by echocardiogram, and higher levels of cardiac Gdf15 mRNA." (PMID 37260376, 2023). "In LPS-treated mice, systemic inflammation and the consequent cardiomyopathy were verified by elevated plasma levels of TNFα, GDF-15, and cardiac troponin I, and by a decrease in the ejection fraction." (PMID 35059851, 2022). "Serum GDF15 concentrations are elevated in sorts of disorders—DM, cardiomyopathy, renal impairment, and cancer." (PMID 32965044, 2021). "We found that cardiac Gdf15 expression in αKOγKO mice was similar to control at 3 days of age, but continued to quickly rise with the development of cardiomyopathy and reached over 30‐fold by 13 days of age over control mice." (PMID 28572090, 2017). "In this study, we show the protective role of GDF15 in septic AKI and cardiomyopathy and attempt to determine the potential mechanisms by which GDF15 is eliciting its role, using a murine model of LPS-induced sepsis." (PMID 28432312, 2017). "To verify the role of MIF and GDF-15 in iPSC-MSCs-CdM for the treatment of Dox-induced cardiomyopathy, we compared the cardioprotective effects of iPSC-MSCs-CdM with immunodepletion of MIF and GDF-15 in iPSC-MSCs-CdM in a mouse model of AIC." (PMID 26057572, 2015). "In subjects with cardiomyopathy who were treated with ivabradine, inflammatory biomarkers, namely tumor necrosis factor α (TNFα), growth-differentiation factor 15 (GDF-15), heart-type fatty acid binding protein (H-FABP), and interleukin 6 (IL-6), were attenuated." (PMID 36769115, 2023). "Novel cardiovascular biomarkers such as GDF-15, H-FABP and sST-2 offer a differential diagnostic value for distinguishing between TTC, DCMP or ICMP and could help in the identification of unclear cardiomyopathies." (PMID 34805296, 2021). "GDF15 may be a sensitive biomarker not only for primary MDs but also for dysmetabolic myopathies and cardiomyopathies." (PMID 34445593, 2021). "Importantly, the development of lethal cardiomyopathy in αKOγKO mice was little affected by cardiac Gdf15 knockdown based on cardiac histology and cardiomyopathy marker Bnp expression." (PMID 28572090, 2017). "Those authors identified genes implicated in cardiac calcium homeostasis (PDE3B), oxidative stress response (FDXR and SPATA18), and the etiology of cardiomyopathy (SGCD, BBC3 and GDF15)." (PMID 33820914, 2021). "Our study suggests that GDF15 is involved in septic AKI and cardiomyopathy and protects the kidney and heart from LPS-induced injury, potentially by acting as an anti-apoptotic and anti-inflammatory mediator." (PMID 28432312, 2017). "To investigate the impact of GDF15 on septic AKI and cardiomyopathy, we treated mice intraperitoneally with 4 mg/kg LPS in PBS or PBS only as a control to induce septic response; this is a commonly used animal model for the study of sepsis." (PMID 28432312, 2017). "Serum GDF-15 levels were significantly higher in patients with cardiomyopathy, as well in those subjects who presented with both nephropathy and cardiomyopathy, compared to subjects without these comorbidities." (PMID 38892211, 2024). "In this analysis, sST-2 and GDF-15 were identified as the paramount biomarkers for identification of a TTC in differential diagnosis to either an ICMP, to a DCMP or to both cardiomyopathies." (PMID 34805296, 2021). "In recent work focusing on the effects of radiation, the objective was to elucidate the underlying molecular mechanisms and to identify genes implicated in cardiac calcium homeostasis (PDE3B), oxidative stress response (FDXR and SPATA18), and the etiology of cardiomyopathy (SGCD, BBC3, and GDF15)." (PMID 34445593, 2021).
cardiomyopathy (continued). "In contrast to cardiac-specific biomarkers, non-cardiac-specific protein biomarkers Gal-3, GDF15 and sST2 appear to be elevated only if an overt clinical phenotype has developed in the different cardiomyopathies." (PMID 33799487, 2021). "Nonetheless, the impact of GDF15 on septic AKI and cardiomyopathy is unclear." (PMID 28432312, 2017). "Consequently, GDF15 may have therapeutic potential for the treatment of septic AKI and cardiomyopathy." (PMID 28432312, 2017). "We hypothesized that GDF15 plays a protective role in LPS-induced AKI and cardiomyopathy." (PMID 28432312, 2017). "Four studies estimated the diagnostic performance of GDF-15 in identifying HFpEF from controls (non-HF population, obese with normal LV function, non-CAD and non-HF population, and population without HFpEF, dilated cardiomyopathy, and ischaemic cardiomyopathy)." (PMID 41180477, 2025). "Similarly elevated soluble suppression of tumorigenicity-2 (sST2), growth differentiation factor-15 (GDF-15) and NT-proBNP may predict biventricular ACM, but no data are available in the context of “Hot phase” cardiomyopathy." (PMID 39786662, 2025).
ischemic stroke (21 papers, 2016 to 2026). A stroke disorder caused by obstruction of blood flow to the brain, due to thrombotic (local blood clot formation) or embolic (due to a blood clot or other material traveling from another site) event. "GDF-15 serum levels at admission are associated with depression later developed in patients with ischemic stroke." (PMID 40529498, 2025). "GDF15 levels are thus associated with the occurrence of a transient ischemic attack and even an ischemic stroke (IS) after adjustment for age and sex." (PMID 39008451, 2024). "The main objective of our study was therefore to assess the association between circulating levels of GDF-15 and three-month all-cause mortality in ischemic stroke patients treated with thrombolysis and/or mechanical thrombectomy." (PMID 31258506, 2019). "It has been proposed that GDF-15 could be associated with poor functional outcomes after ischemic stroke." (PMID 31258506, 2019). "GDF-15 may therefore have a predictive power in addition to clinical and biologic variables for the mortality risk evaluation after ischemic stroke." (PMID 31258506, 2019). "Furthermore, other studies have described an association between rising GDF-15 levels and functional outcome after an ischemic stroke." (PMID 31624933, 2019). "Combination of GDF-15, aCL, aPS and MMP-9 substantially improved the risk prediction of depression at 3 months after ischemic stroke." (PMID 40529498, 2025). "This study aims to assess the sources of GDF15 production following an experimental ischemic stroke." (PMID 39008451, 2024). "There is some evidential support for central as well as peripheral expression of GDF15 in response to ischemic stroke." (PMID 39737171, 2024). "In a previous study, the GDF-15 level was significantly elevated in patients after ischemic stroke with poor outcomes, however, the degree of brain damage reflected by the NIHSS score on admission was not severe." (PMID 37446186, 2023). "High levels of serum growth differentiation factor-15 are significantly associated with poor clinical outcomes in acute ischemic stroke, suggesting that serum growth differentiation factor-15 levels can predict the prognosis of ischemic stroke patients." (PMID 38020612, 2023). "Recent data from our research unit also revealed that ischemic stroke in rats leads to a rapid and persistent increase of GDF-15 in blood circulation." (PMID 31258506, 2019). "Our results are consistent with two other studies in which GDF-15 levels declined between 6 h and 7 days after ischemic stroke in 57 patients and between admission and 24 h in 264 patients." (PMID 31258506, 2019). "Recent experimental data from our team revealed that ischemic stroke in rats prompted the increase in GDF-15 in the circulation 2 and 24 h after cerebral embolization." (PMID 31258506, 2019). "However, little has been explored about the impact of metformin on the GDF-15 signaling in ischemic stroke." (PMID 40489027, 2025). "However, understanding the origins, targets and functions of GDF15 in clinical situations, such as ischemic stroke, remains a complex challenge." (PMID 39008451, 2024). "Our findings further suggest that the GDF-15 cytokine could be a prognostic biomarker of mortality in ischemic stroke patients treated with acute revascularization therapy." (PMID 31258506, 2019). "In contrast, there is little available data concerning GDF-15 involvement in ischemic stroke." (PMID 31258506, 2019). "Our findings suggest that admission GDF-15 may be an additional biomarker to predict the outcomes of ischemic stroke patients who specifically receive acute revascularization therapy." (PMID 31258506, 2019). "Accordingly, this review aims to discuss the role of metformin in the neuropathology of ischemic stroke regarding the AMPK and GDF-15 signaling pathways." (PMID 40489027, 2025).
viral infections (21 papers, 2011 to 2024). "Recently, bacterial or viral infections have been associated with secretion of GDF15 and an adaptive response in order to increase pathogen tolerance." (PMID 32723474, 2020). "Although these studies report the association of GDF-15 with increased susceptibility to viral infection, chronic inflammation and senescence in the context of COPD and cigarette smoke exposure, they introduce possible mechanisms by which baseline GDF-15 increases future pneumonia risk." (PMID 38105941, 2023). "Furthermore, GDF-15 appears as a marker for all-cause mortality in the elderly and constitutes a predictor of disease severity during bacterial and viral infections." (PMID 35251002, 2022). "In viral infections, GDF15 acts by attenuating antiviral immune responses, significantly affecting the outcome of the disease." (PMID 37408184, 2023). "Since the role of GDF15 is still controversial in various viral infections, more studies are needed to elucidate the molecular mechanism of GDF15 in YSK-A-treated SARS-CoV-2 infection." (PMID 38057373, 2023). "Altogether, our findings demonstrate that CS exposure leads to higher viral infection in human bronchial epithelium by altering not only interferon responses, but likely also through a switch to glycolysis, and via GDF15-related pathways." (PMID 37612597, 2023). "In brief, there is a conflicting controversy regarding the possible role of GDF15 in various viral infections." (PMID 36140453, 2022). "In vitro and animal models recently identified GDF-15 as an amplifier of lung inflammation during viral infections, therefore representing a major pathogenetic mechanism of susceptibility and disease severity in patients with already damaged airways." (PMID 36552007, 2022). "Except for viral infection, GDF15 levels in patients with other pathogens also were higher than those in nonsepsis group." (PMID 34566964, 2021). "Other metabolic factors, including FGF21, BMP7, and GDF15, trended up upon virus infection, presumably due to a compensatory effect as these three secreted proteins were involved in positively maintaining metabolic homeostasis." (PMID 34916489, 2021). "Using a GDF15-blocking antibody to inhibit GDF15 activity, the authors demonstrated that GDF15 inhibition increased mortality in mouse models of bacterial and viral infection." (PMID 32310257, 2020). "The GDF15 regulates host immune defense against various viral infections." (PMID 36140453, 2022). "In addition, GDF15, also known as an inflammation-related hormone, is induced by inflammation and is necessary for surviving bacterial and viral infections, and sepsis." (PMID 35610317, 2022). "However, the correlations between the GDF15 expression level and virus infections (especially for hepatitis viruses) are undefined." (PMID 21625435, 2011). "Studies have shown that GDF15 is related to inflammatory cytokines, such as IL-6 and CRP, suggesting an essential role in maintaining inflammation throughout viral infections." (PMID 37408184, 2023). "An induction of GDF-15 has been reported and described in numerous diseases,such as CVD, cancers, metabolic disorders, rheumatic diseases and viral infection." (PMID 39077481, 2023).